PSEN1 (presenilin 1)
Diseases named in the same sentence as PSEN1 in open-access papers (continued):
Sharing a sentence is not in itself a finding about the gene and the disease.
Alzheimer disease (continued). "Mutations in the Amyloid Precursor protein (APP), Presenilin 1 (PSEN1) and Presenilin 2 (PSEN2) genes and duplications of the APP locus are the main causes of autosomal dominant early-onset Alzheimer's disease." (PMID 29875629, 2018). "PSEN1 Thr116Ile was initially discovered in an Italian patient and two French families with early onset Alzheimer’s disease (EOAD) with similar age of onset." (PMID 30200536, 2018). "PSEN1/2 and APP gene mutations have been linked to early-onset, autosomal dominant familial forms of Alzheimer’s disease (FAD)." (PMID 30309378, 2018). "It is known that dormant inherited mutations in APP, PSEN1, and PSEN2 lead to early onset Alzheimer’s disease (EOAD) and mutations in MAPT, GRN and C9ORF72 cause familial FTD." (PMID 30090657, 2018). "Dominantly inherited mutations in amyloid precursor protein (APP), presenilin 1 (PSEN1), and presenilin 2 (PSEN2) cause early-onset Alzheimer disease (AD)." (PMID 30045758, 2018). "Familial Alzheimer's disease (FAD): a form of Alzheimer's disease caused by mutations in a specific set of genes (APP, PSEN1 and PSEN2) that are passed down from parents to offspring in an autosomal-dominant manner." (PMID 29784664, 2018). "Mutations in the APP, PSEN1, and PSEN2 genes cause early onset Alzheimer’s disease (EOAD) that follows a Mendelian inheritance pattern." (PMID 29740579, 2018). "Familial Alzheimer’s disease (FAD), due to dominantly inherited mutations in the presenilin 1 (PSEN1), PSEN2, and amyloid precursor protein (APP) genes, accounts for a small proportion (approximately 1%) of all cases of AD." (PMID 29562504, 2018). "Mutations in the amyloid protein precursor (APP), presenilin-1 (PSEN1), and presenilin-2 (PSEN2) genes are a known cause of familial, early-onset Alzheimer disease (EOAD) (onset below age 65)." (PMID 28350801, 2017). "Amyloid protein precursor (APP), presenilin-1 (PSEN1), and presenilin-2 (PSEN2) mutations cause autosomal dominant forms of early-onset Alzheimer disease (AD-EOAD)." (PMID 28350801, 2017). "Amyloid-β precursor protein (AβPP), presenilin 1 (PSEN1), and presenilin 2 (PSEN2) genes have been strongly implicated in early onset Alzheimer’s disease (EOAD), particularly familial EOAD, which comprise less than 5% of Alzheimer’s cases." (PMID 28373857, 2017). "In another work concerning ATF4, APP/PS1 mice (double transgenic mice expressing a chimeric mouse/human amyloid precursor protein and a mutant human presenilin 1 in their neurons), an established animal model of Alzheimer’s disease, was used." (PMID 29065505, 2017). "The significance of PSEN1 in pathology has been widely presented in Alzheimer's disease and other neurodegenerative disorders, as it generates amyloid β." (PMID 27888801, 2017). "For example, in Alzheimer's disease, we noted that all associated genes (APP, PSEN1, and PSEN2) were reported to show an increase in Aβ in neurons (Fig EV3A)." (PMID 29051230, 2017). "The intramembrane proteolytic activities of presenilins (PSEN1/PS1 and PSEN2/PS2) underlie production of β-amyloid, the key process in Alzheimer’s disease (AD)." (PMID 29137240, 2017). "Mutations in PSEN1 and PSEN2 are major causative genetic factors of familial cases of Alzheimer’s disease (AD), characterized by early onset AD manifestation." (PMID 29137240, 2017). "Here, we studied the organization of in vitro gamma oscillations in the MEC and LEC of the transgenic (tg) amyloid precursor protein (APP)-presenilin 1 (PS1) mouse model of Alzheimer’s Disease (AD) at 4–5 months of age." (PMID 27833535, 2016). "Mutations in APP, APOE, PSEN1, PSEN2 and MAPT genes were found to cause Alzheimer’s disease pathogenesis." (PMID 26784894, 2016). "In contrast, the identification of PSEN1, a well-known familial Alzheimer’s disease gene as an important node in both direct interaction and shortest-path network is critical in number of ways." (PMID 26784894, 2016).
Alzheimer disease (continued). "Familial Alzheimer’s disease (AD), mostly associated with early onset, is caused by mutations in three genes (APP, PSEN1, and PSEN2) involved in the production of the amyloid β peptide." (PMID 25914626, 2015). "A role of MAM has been recently proposed in another neurodegenerative disorder that is Alzheimer's disease with the demonstration that presenilin 1 and 2 are predominantly located into these specialized structures." (PMID 26136767, 2015). "ACHE inhibitors are investigated largely as a treatment option for Alzheimer’s disease and an interaction was found between ache and presenilin-1 levels." (PMID 24548546, 2014). "This set comprised the combination of the MeSH terms “Alzheimer Disease”, “Amyloid beta-Peptides”, “Amyloid beta-Protein Precursor”, “Presenilin-1”, “Apolipoprotein E4”, “Plaque, Amyloid”, and “tau Proteins”." (PMID 24917541, 2014). "Alzheimer's disease (AD) is a complex disorder with some cases known to be caused by mutations in 3 genes: the amyloid precursor protein (APP), Presenilin 1 (PSEN1), and Presenilin 2 (PSEN2)." (PMID 24958194, 2014). "APP/PS1 double-transgenic mouse models of Alzheimer's disease (AD), which overexpress mutated forms of the gene for human amyloid precursor protein (APP) and presenilin 1 (PS1), have provided robust neuropathological hallmarks of AD-like pattern at early ages." (PMID 24089686, 2013). "Despite the extensive mechanistic and pathological characterization of the amyloid precursor protein (APP)/presenilin-1 (PS-1) knock-in mouse model of Alzheimer's disease (AD), very little is known about the AD-relevant behavioral deficits in this model." (PMID 23705774, 2013). "Mutations linked to early onset, familial forms of Alzheimer's disease (FAD) are found most frequently in PSEN1, the gene encoding presenilin-1 (PS1)." (PMID 22529981, 2012). "Familial Alzheimer’s disease is associated with mutations in one of three possible genes: APP on chromosome 21, PSEN1 on chromosome 14 or PSEN2 on chromosome 1." (PMID 22654716, 2011). "Mutations in PSEN1 and PSEN2 genes, which encode polytopic proteins termed presenilin 1 (PS1) and presenilin 2 (PS2), respectively, cause autosomal dominant early-onset familial Alzheimer's disease (FAD)." (PMID 20798900, 2010). "The APP/PS1 mouse model used in our study possesses concurrent mutated forms of APP and Presenilin 1 (PS1), both identified separately in human Alzheimer diseases." (PMID 19551139, 2009). "Presenilin 1 (PS1) encodes a ubiquitously expressed, eight-transmembrane protein involved in most cases of early-onset Familial Alzheimer's disease (FAD)." (PMID 19114997, 2008). "In triple transgenic Alzheimer's disease mice expressing three mutant transgenes (amyloid precursor protein [double Swedish, K670M/N671L], presenilin 1 [M146V], and tau [P301L]), β amyloid accumulation occurs before tau hyperphosphorylation." (PMID 19091000, 2008). "Approximately, 150 mutations in human PSEN1 and ten mutations in human PSEN2 have been associated with early onset Alzheimer's disease." (PMID 17854491, 2007). "Mutations in PSEN1 and PSEN2 are autosomal dominant, highly penetrant, and cause Alzheimer's disease (AD) symptoms before age 65, in some cases with onset of symptoms less than 30 years of age." (PMID 16930451, 2006). "We examined the local and global contributions of amyloid-β and tau pathology to glucose metabolism and their interplay in memory decline in Presenilin-1 E280A mutation carriers and non-carriers from the largest autosomal-dominant Alzheimer’s disease kindred." (PMID 41567829, 2026). "These technologies, including whole-exome sequencing (WES) and whole-genome sequencing (WGS), have facilitated the identification of pathogenic mutations in genes such as APP, PSEN1, and PSEN2 in Alzheimer’s disease (AD), as well as LRRK2, SNCA, and PINK1 in Parkinson’s disease (PD)." (PMID 40076852, 2025).
Alzheimer disease (continued). "Numerous genes involved in the pathogenesis of Alzheimer disease have been described so far, including, but not limited to, mutations in amyloid precursor protein (APP), presenilin 1 and 2 (PSEN1 and PSEN2), and carrying the E4 allele of Apolipoprotein (ApoE) genes." (PMID 39199306, 2024). "Although Alzheimer’s disease arises predominantly as a sporadic condition of late adult life, there are rarer early-onset Mendelian forms caused by mutations in the APP gene or in genes (PSEN1 and PSEN2) known to alter its enzymatic cleavage." (PMID 38287166, 2024). "Additionally, mutations in the amyloid precursor protein (APP), presenilin 1 (PSEN1), and presenilin 2 (PSEN2) genes have been identified in patients with an autosomal-dominant form of early-onset Alzheimer’s disease." (PMID 38926887, 2024). "Additionally, BP effectively reduces β-amyloid accumulation and improve short-term memory in an Alzheimer’s disease (AD) mouse model by modulating the LncCYP3A43-2/miR29-2-5p/PSEN1 network." (PMID 39509425, 2024). "Familial Alzheimer's disease is characterized by a strong genetic component and is typically associated with mutations in specific genes, including those coding for amyloid precursor protein (APP), presenilin 1 (PSEN1), and presenilin 2 (PSEN2)." (PMID 38169888, 2024). "The mother had been diagnosed with multiple sclerosis, her son with hereditary spastic paraplegia, and the diagnosis of Alzheimer’s disease was not considered until whole-genome sequencing revealed the PSEN1 variant." (PMID 36895955, 2023). "To test this hypothesis, we used the 5xFAD mouse model of Alzheimer’s disease that expresses human APP and presenilin 1, encoding five human pathogenic mutations that cause familial Alzheimer’s disease." (PMID 37171075, 2023). "Additionally, genetic factors, such as mutations in genes like amyloid precursor protein (APP) and presenilin 1 and 2 (PSEN1 and PSEN2), can further increase the risk of developing Alzheimer’s disease." (PMID 37688657, 2023). "Specifically, the study found that mice with amyloid precursor protein and presenilin 1 gene variations, which are associated with early-onset Alzheimer’s disease but not all-cause dementia, had lower vitamin D levels." (PMID 37629597, 2023). "Moreover, within a single substrate, APP, and with one enzyme, presenilin-1, multiple cut sites are thought to affect downstream Alzheimer's disease progression." (PMID 38270390, 2023). "Interestingly, the Lep-HFD group exhibited reduced expression of Psen1, coding for a crucial protein linked to the metabolism of the amyloid precursor protein (APP) and associated with Alzheimer’s disease (AD)." (PMID 38203399, 2023). "Familial Alzheimer’s disease (FAD) is known to be associated with mutations in the APP, PSEN1, and PSEN2 genes involved in Aβ production; however, these genetic defects occur in only about 10–20% of FAD cases, and more genes and new mechanism causing FAD remain largely obscure." (PMID 37365538, 2023). "Early-onset Alzheimer’s disease (EOAD) is an autosomal dominantly inherited disease, in which a founder effect has been described for A431E mutation in the PSEN1 gene, with most of the affected patients being residents of a small town in the state of Jalisco in Mexico." (PMID 36979311, 2023). "The associations of non‐pathogenic variants of APP, PSEN1, and PSEN2 with Alzheimer's disease (AD) remain unclear." (PMID 36217304, 2023). "Substrate switching induced mitochondrial depolarization, but not dysmorphology, in Alzheimer’s disease cells carrying three different PSEN1 mutations, wherein mitofusin activation had no consistent effect." (PMID 35326504, 2022). "However, only 5–10% of patients with early-onset Alzheimer’s disease are carrying a pathogenic mutation in APP, PSEN1, PSEN2, or the common apolipoprotein E (APOE) ɛ4 allele." (PMID 36077172, 2022).
Alzheimer disease (continued). "Interestingly, all of them, except for PSEN1 (a transmembrane protein involved in Alzheimer’s disease), were transcription factors." (PMID 35565454, 2022). "This work is an extension of current research, in which we present new changes in the genes related to Alzheimer’s disease, such as the amyloid protein precursor, β-secretase, presenilin 1, and presenilin 2, in the circulating lymphocytes of neonates with perinatal asphyxia treated with hypothermia." (PMID 35743334, 2022). "The APP/PSEN1 mouse, a transgenic mouse that overexpresses both the amyloid precursor protein (APP) and presenilin 1 (PSEN1), is a pathological model for amyloid-β plaque formation, a hallmark and a primary pathogenic indicator of Alzheimer’s disease." (PMID 36234722, 2022). "Moreover, in familial Alzheimer’s disease, PSEN1 mutation inhibited PI3K/AKT signal activation, leading to cell apoptosis and progression of Alzheimer’s disease." (PMID 34568005, 2021). "Additionally, known highly penetrant genetic variants from familial-based cohorts with early-onset Alzheimer’s disease (EOAD) implicate genes such as APP, PSEN1, and PSEN2." (PMID 33947463, 2021). "PSEN1 is mainly related to Alzheimer's disease and may be involved in the cleavage of the Notch receptor." (PMID 34335753, 2021). "Further investigation of ADAM9, AGAP2 and PSEN1 levels in human subjects with APP-related disorders could help in understanding Alzheimer’s disease and autism spectrum disorders." (PMID 32612155, 2020). "The beneficial effect of TRPC6 to Alzheimer’s disease was demonstrated by showing that stimulating TRPC6 or the store-operated Ca2+ entry improved hippocampal long-term potentiation of the APP-presenilin 1 mutant mice, an experimental model of Alzheimer’s disease." (PMID 33490083, 2020). "Moreover we report the prevalent role of APP-Aβ degradation genes upon genes involved in APP-Aβ production as well as Mendelian genes causative for Alzheimer’s disease (APP, PSEN1 and PSEN2)." (PMID 32345996, 2020). "Furthermore, treatment of Alzheimer's disease transgenic mice (dual transgenic expressing mutant forms of both App and Psen1 genes) with phenylbutyrate resulted in a reduction of amyloid plaques in the cortex and hippocampus." (PMID 31368626, 2019). "Approximately 1–6% of all cases are classed as early-onset AD, typically with mutations in amyloid-processing genes (APP, PSEN1 and PSEN2), whilst genome wide-association studies (GWAS) have identified numerous risk variant genes associated with late onset Alzheimer’s disease (AD)." (PMID 30124174, 2018). "Mutations that are established to be pathogenic in APP and PSEN1 were found in either a clinical DLB case; or in pathologically confirmed DLB cases, of which 69% of the cohort also met pathological criteria for Alzheimer’s disease." (PMID 30097731, 2018). "In AßPP/PS1 (presenilin 1) double mutant transgenic mouse model of Alzheimer's disease, EGCG restored mitochondrial respiratory rates, mitochondrial membrane potential (MMP), reactive oxygen species (ROS) and ATP levels in several brain regions including hippocampus, cortex, and striatum." (PMID 29163766, 2017). "The role of Vit C in AD disease was studied in APP/PSEN1 mice carrying human AD mutations in the amyloid precursor protein (APP) and presenilin (PSEN1) genes (transgenic mouse model of Alzheimer’s disease) with partial ablation of vitamin C transport in the brain." (PMID 28654017, 2017). "Interestingly, PSEN1 and APP, genes whose mutation are known to be linked to early onset Alzheimer’s disease, are closely linked to this pathway." (PMID 27585646, 2016). "Additionally, alterations in critical signals regulating neurogenesis, such as presenilin-1, Notch 1, soluble amyloid precursor protein, CREB, and β-catenin underlie dysfunctional neurogenesis in Alzheimer's disease." (PMID 27199641, 2016). "A vast number of genes regulate Alzheimer’s disease, including Presenilin 1 (PSEN1)." (PMID 27357204, 2016).
Alzheimer disease (continued). "PSEN1 encodes a protein that regulates the processing of amyloid precursor protein (APP) and is mutated in familial forms of Alzheimer’s disease while DPF3 function is associated with the BAF chromatin remodeling complex to promote transcription during development." (PMID 25969726, 2015). "Mutations in three genes, amyloid precursor (APP), presenilin 1 (PSEN1) and presenilin 2 (PSEN2), play extremely important roles in the metabolism of Aβ, and these mutations have been identified as risk factors for Early Onset Alzheimer Disease (EOAD)." (PMID 24586483, 2014). "Also the relative contribution of PSEN1, PSEN2, and APP mutations to early onset Alzheimer's Disease (EOAD) is the subject of considerable controversy, and mutation frequency is highly dependent upon the studied population." (PMID 24377094, 2013). "Less than 1% of Alzheimer's disease cases are familial, with autosomal dominant mutations described in only three genes that lead to early onset disease; APP, presenilin 1 (PSEN1) and presenilin 2 (PSEN2), both of the latter encoding components of the γ-secretase pathway." (PMID 24133413, 2013). "Furthermore, we can see that apolipoprotein E4, membrane proteins, amyloid beta-protein precursor, amyloid beta-peptides, presenilin-1, tau proteins, and peptide fragments, are all closely connected to Alzheimer disease." (PMID 23825632, 2013). "APP/PS1 double-transgenic mouse models of Alzheimer’s disease (AD), which overexpress mutated forms of the gene for the human amyloid precursor protein (APP) and presenilin 1 (PS1), have provided robust neuropathological hallmarks of an AD-like pattern at early ages." (PMID 29805876, 2013). "Mutations in human PSEN1 cause Alzheimer's disease and it is noteworthy that none of the amino acid changes between pig and human are located in positions known to cause Alzheimer's disease." (PMID 17854491, 2007). "One type of ADRD, early-onset Alzheimer’s disease (EOAD), afflicts about 5% of the population diagnosed with ADRD, while mostly heritable, the known genes associated with this prognosis are amyloid precursor protein (APP), presenilin 1 (PSEN1), and presenilin 2 (PSEN2)." (PMID 38967905, 2025). "Presenilin 1 (PSEN1) and amyloid precursor protein (APP) are well-established genetic factors associated with early-onset familial Alzheimer’s disease (EOFAD), whereas apolipoprotein E4 (APOE4) is a recognized genetic risk factor for sporadic late-onset Alzheimer’s disease (LOAD)." (PMID 40244244, 2025). "We asked whether activation of the hypoxia-inducible factor (HIF) pathway via genetic deficiency of HIF prolyl 4-hydoxylase-2 (HIF-P4H-2; also known as PHD2/EGLN1) could be an Alzheimer’s disease–modifying therapy using transgenic amyloid precursor protein (APP)/presenilin 1 (PS1) female mice." (PMID 40609789, 2025). "While most of the Alzheimer’s disease (AD) cases are sporadic and manifest after age 65 (late-onset AD, LOAD), a subset of patients develop symptoms earlier in life (early-onset, EOAD) due to mutations in the PSEN1, PSEN2, or APP genes with an autosomal-dominant inheritance pattern (AD-EOAD)." (PMID 40869250, 2025). "To summarize, we present an in-depth characterization of an extreme form of autosomal dominant Alzheimer’s disease caused by a novel mutation in PSEN1 with onset in the early 20s presenting with SP that was not diagnosed as Alzheimer’s disease until whole-genome sequencing was performed." (PMID 36895955, 2023). "In addition, the expression of Presenilin 1 was negatively regulated by the non-CpG methylation level associated with the promoter in Alzheimer’s disease (AD) samples." (PMID 37047150, 2023). "Diffusion parameters were significantly and dramatically affected in widespread brain areas in relation to the F388S PSEN1 mutation, intermediate in association with the A431E PSEN1 mutation, and lowest with other autosomal dominant Alzheimer’s disease mutations not causing SP." (PMID 36895955, 2023).